LAP3P2 (leucine aminopeptidase 3 pseudogene 2)
Gene: Processed pseudogene on chromosome 6 (36,673,817 to 36,675,270, forward strand). Ensembl gene ENSG00000213500.
Diseases named in the same sentence as LAP3P2 in open-access papers:
LAP3P2 is named in the same sentence as 1 disease in open-access papers, as found by Europe PMC text mining. Sharing a sentence is not in itself a finding about the gene and the disease. The quoted sentences say what the papers report.
Hypertension (1 paper, 2020). The presence of chronic increased pressure in the systemic arterial system. "We also conducted correlation analysis between LOC646616, LAP3P2, hsa_circ_0039388, and hsa_circ_0038648 and general clinical data in the hypertension group." (PMID 32392180, 2020).